DEPDC1B (DEP domain containing 1B)
Synonyms: XTP1; BRCC3
Tractability: PROTAC: ubiquitination databases record sites on it.
Gene: Protein-coding gene on chromosome 5 (60,596,912 to 60,700,194, reverse strand). Ensembl gene ENSG00000035499.
Subcellular location (Human Protein Atlas): Golgi apparatus; Cytosol; Nucleoplasm
Pathways (Reactome):
Signal Transduction: CDC42 GTPase cycle; RAC1 GTPase cycle; RAC2 GTPase cycle; RAC3 GTPase cycle; RHOA GTPase cycle; RHOB GTPase cycle; RHOC GTPase cycle; RHOD GTPase cycle; RHOF GTPase cycle; RHOG GTPase cycle; RHOJ GTPase cycle; RHOQ GTPase cycle; RHOU GTPase cycle; RHOV GTPase cycle; RND1 GTPase cycle; RND2 GTPase cycle; RND3 GTPase cycle
Gene Ontology:
Biological process: cell migration; positive regulation of Wnt signaling pathway; intracellular signal transduction; signal transduction
Genetic constraint (gnomAD): Loss-of-function variants: 41 observed, 55.49 expected, observed/expected ratio (o/e) 0.74, 90% interval 0.57 to 0.96. The upper end of that interval is the gene's LOEUF score, 0.96, which puts it in group 4 of 6, group 1 being the genes least tolerant of losing a copy. Missense variants: 526 observed, 613.68 expected, observed/expected ratio (o/e) 0.86, 90% interval 0.8 to 0.92. Synonymous variants: 211 observed, 217.79 expected, observed/expected ratio (o/e) 0.97, 90% interval 0.87 to 1.09.
Homologues: Orthologues: chimpanzee DEPDC1B (99% identical), macaque DEPDC1B (99% identical), pig DEPDC1B (96% identical), dog DEPDC1B (95% identical), rat Depdc1b (94% identical), mouse Depdc1b (94% identical), guinea pig DEPDC1B (94% identical), rabbit DEPDC1B (86% identical), tropical clawed frog depdc1b (68% identical), Caenorhabditis elegans let-99 (17% identical). Paralogues in human: DEPDC1 (53% identical), DEPDC7 (22% identical), DEPDC4 (17% identical).
Diseases named in the same sentence as DEPDC1B in open-access papers:
DEPDC1B is named in the same sentence as 38 diseases in open-access papers, as found by Europe PMC text mining. Sharing a sentence is not in itself a finding about the gene and the disease. The quoted sentences say what the papers report.
malignant melanoma (10 papers, 2020 to 2023). "In agreement with this, both loss‐ and gain‐of‐function studies demonstrated that DEPDC1B was required and sufficient for melanoma growth, tumorigenicity, invasion and angiogenesis in vitro and in vivo." (PMID 35088579, 2022). "Previous study reported that knockdown of DEPDC1B inhibited the proliferation of malignant melanoma cells." (PMID 37056386, 2023). "Analysis of the TCGA dataset revealed a substantial portion of melanoma patients exhibited high levels of DEPDC1B transcripts in cutaneous melanoma tissues (n = 461) compared with normal tissues (n = 558)." (PMID 35088579, 2022). "How these secreted factors are regulated by DEPDC1B and their contribution to its oncogenic properties at different stages of melanoma development warrant further investigation." (PMID 35088579, 2022). "Treatment of SOX10 KD cells with DEPDC1B OE resulted in the partial rescue of melanoma cell proliferation, colony formation, invasion, lung metastasis, and CD31+ microvessel formation in lung nodules compared with SOX10 KD alone." (PMID 35088579, 2022). "Here, we demonstrated that SOX10 regulates expression of DEPDC1B which sequesters ubiquitin ligase CDC16 to stabilize the secreted SCUBE3 protein for promoting melanoma growth, angiogenesis, and metastasis." (PMID 35088579, 2022). "Consistently, DEPDC1B is both required and sufficient for melanoma growth, metastasis, angiogenesis, and functions as a direct downstream target of SOX10 to partly mediate its oncogenic activity." (PMID 35088579, 2022). "To establish the clinical relevance of DEPDC1B and SCUBE3 on angiogenesis, we analyzed their expression in association with CD31 in a melanoma tissue microarray." (PMID 35088579, 2022). "Tissue microarray analysis indicates that DEPDC1B expression is positively correlated with SOX10 in the different stages of melanoma." (PMID 35088579, 2022). "To this end, we used TOPflash reporter to measure the transcriptional activity of nuclear β‐catenin as a readout for canonical Wnt signaling in three melanoma cell lines treated with DEPDC1B KD or OE." (PMID 35088579, 2022). "Our findings demonstrated that SCUBE3 OE partially restored melanoma angiogenesis and metastasis in DEPDC1B KD cells, implying additional factors are required." (PMID 35088579, 2022). "Taken together, these data demonstrate the oncogenic role of DEPDC1B in promoting melanoma metastasis and angiogenesis." (PMID 35088579, 2022). "For example, knockdown of DEPDC1B inhibits the cellular behavior of malignant melanoma by slowing cell proliferation and inducing apoptosis." (PMID 36568241, 2022). "Immunofluorescence analysis of a tissue microarray showed extensive overlap in the expression of SOX10, which is as key driver of melanoma initiation and progression, and the expression of DEPDC1B in the different stages of melanoma." (PMID 35088579, 2022). "An oncogenic mechanism is unraveled by which DEPDC1B functions downstream of SOX10 to promote melanoma angiogenesis and metastasis." (PMID 35088579, 2022). "Although the precise function of DEPDC1B is uncertain, it is reported that DEPDC1B knockdown can inhibit tumor growth in malignant melanoma and some other types of malignant tumors." (PMID 34032605, 2021). "An increasing body of evidence clarified that abnormal overexpression of DEPDC1B in diverse types of cancers, including non-small cell lung cancer, soft tissue sarcoma, cervical cancer, malignant melanoma, and hepatocellular cancer." (PMID 33203836, 2020). "More recently, it was demonstrated that the KD of DEPDC1B inhibits the occurrence of malignant melanoma by inhibiting cell proliferation and inducing cell apoptosis." (PMID 33203836, 2020). "Since previous studies have shown that DEPDC1B promotes angiogenesis and metastasis of melanoma by competing with CDC16 to promote SCUBE3 secretion, we investigated whether a similar phenomenon exists in breast cancer." (PMID 37642235, 2023).
malignant melanoma (continued). "Knockdown of DEPDC1B could inhibit the proliferation of malignant melanoma cells, whereas knockdown of DEPDC1B could markedly promote cell apoptosis." (PMID 37056386, 2023). "To examine whether DEPDC1B functions downstream of SOX10 to regulate melanoma growth and metastasis, we performed an epistasis analysis." (PMID 35088579, 2022). "This study unravels a new molecular mechanism of DEPDC1B acting downstream of SOX10 to promote melanoma angiogenesis and metastasis through CDC16 sequestration that stabilizes secreted SCUBE3, which suggests the possibility of targeting SCUBE3 as a therapeutic strategy against metastatic melanoma." (PMID 35088579, 2022). "To further examine DEPDC1B protein expression in melanoma tissue samples, we performed immunofluorescence staining in a melanoma tissue microarray (TMA), which contained 62 cases of primary melanoma, 22 metastatic malignant melanoma, 14 nevus tissues, and two skin tissues." (PMID 35088579, 2022). "However, only a few melanoma specimens (n = 5) showed DEPDC1B amplification and most (n = 434) were diploid, suggesting other factors contributed to the increase in DEPDC1B transcription." (PMID 35088579, 2022). "A previous report also showed that DEPDC1B is required for melanoma growth and survival, but whether it has a role in melanoma metastasis remains to be determined." (PMID 35088579, 2022). "Some studies indicated that the downregulation of DEPDC1B expression could suppress cell proliferation by promoting apoptosis in malignant melanoma, bladder cancer, and glioblastoma." (PMID 35095994, 2021). "As previous studies showed that DEPDC1B enhanced migration and invasion of non‐small‐cell lung cancer through the activation of canonical Wnt/β‐catenin pathway, we investigated whether a similar phenomenon occurs in melanoma cells." (PMID 35088579, 2022). "It is worth noting that it was reported that DEPDC1B promotes SCUBE3 secretion through competitive binding with ubiquitin ligase CDC16, thus promoting angiogenesis and metastasis of melanoma." (PMID 37642235, 2023). "The expression of DEPDC1B was higher in LIHC tissues than in normal tissues, and this is consistent with the results in non-small cell lung cancer, oral cancer, malignant melanoma, bladder cancer, glioblastoma, and pancreatic cancer." (PMID 35095994, 2021). "Furthermore, increasing evidence in recent years suggests that the overexpression of DEPDC1B is associated with tumor aggressiveness and poor prognosis in cancers, such as oral cancer, malignant melanoma, glioblastoma, non-small cell lung, and pancreatic cancers." (PMID 35095994, 2021). "Importantly, expression of SOX10, DEPDC1B, and SCUBE3 are positively correlated with microvessel density in the advanced stage of melanomas." (PMID 35088579, 2022). "DEPDC1B competitively interacts with CDC16 in the cytosol to block the ubiquitination and degradation of SCUBE3, enabling stabilized SCUBE3 to be secreted from melanoma cells for blood vessel recruitment to facilitate their growth, survival, and metastasis." (PMID 35088579, 2022). "Altogether, these results demonstrate that SOX10 and DEPDC1B are clinically correlated with SCUBE3 and CD31 expressions in advanced stages of melanoma, consistent with their regulatory relationship in promoting melanoma angiogenesis and metastasis." (PMID 35088579, 2022). "Nevertheless, the regulation of DEPDC1B by SOX10 is further supported by their co‐expression in most biopsies from different stages of melanoma, strongly suggesting that SOX10 is one of the upstream factors contributing to the abnormal upregulation of DEPDC1B expression in melanoma." (PMID 35088579, 2022). "In contrast to other cancer types, the ability of DEPDC1B to enhance the metastatic potential of melanoma does not dependent on the activities of Rho GTPase signaling and canonical Wnt signaling, but involves the secretion of SCUBE3, which was shown to promote angiogenesis in vitro and in vivo." (PMID 35088579, 2022).
malignant melanoma (continued). "Similarly, DEPDC1B SHCBP1, RRM2, PLK1, and UHRF1 have been found to promote melanoma proliferation and could be potential targets for treatment; their coefficients were all positive, which implies that they had an additive effect on the risk scores." (PMID 34384498, 2021). "Moreover, accumulating evidence demonstrated that DEPDC1B is overexpressed in diverse types of cancers such as non-small cell lung cancer, oral cancer, prostate cancer, soft tissue sarcoma, cervical cancer, and malignant melanoma." (PMID 36568241, 2022). "In addition, immunofluorescence staining in melanoma tissue arrays showed that expression levels of SOX10, DEPDC1B and CDC16 were high in nevi which do not metastasize but SCUBE3 was barely detectable." (PMID 35088579, 2022).
oral cancer (10 papers, 2014 to 2025). "Su found that DEPDC1B plays a role in the development of oral cancer and revealed that proliferation was linked to a novel DEPDC1B–Rac1–ERK1/2 signaling axis in oral cancer cell lines." (PMID 32684847, 2020). "We revealed that proliferation was linked to a novel DEPDC1B-Rac1-ERK1/2 signaling axis in oral cancer cell lines." (PMID 25091805, 2014). "We revealed that the proliferation was linked to the DEPDC1B-Rac1-ERK1/2 signaling axis in the oral cancer cell lines." (PMID 25091805, 2014). "Specific proteins, including DEP Domain Containing 1B (DEPDC1B), demonstrate enhanced expression levels in oral cancer samples compared to normal adjacent tissues." (PMID 40096320, 2025). "Ahuja P and Singh K showed that DEPDC1B promoted oral cancer cell growth, invasion, and anchorage independent growth mediated by the interaction between DEPDC1B and Rac1." (PMID 34032605, 2021). "DEPDC1B, downregulated in the presence of E2 protein, was recently found to be overexpressed in oral cancer, which can possibly be explained by the disruption of the E2 open reading frame upon the integration of viral genome into the host genome." (PMID 27034663, 2016). "E2 is known to interact with and downregulate several proteins (CPB2, HSPBAP1, RBM26, etc.), one of them being DEPDC1B, which recently was found to be overexpressed in oral cancer." (PMID 27034663, 2016). "We confirmed that the cell proliferation ability induced by DEPDC1B was abolished with the coexpressed Rac1 N17 proteins in oral cancer cells." (PMID 25091805, 2014). "Among the 7 oral cancer tissues that were evaluated, 6 overexpressed DEPDC1B proteins in comparison with normal adjacent tissue." (PMID 25091805, 2014). "Our data revealed that DEPDC1B affected Rac1 GTP loading and augmented ERK1/2 activity, causing subsequent colony formation in oral cancer cells." (PMID 25091805, 2014). "We then demonstrated that DEPDC1B proteins promoted anchorage-independent growth in the KB cultured oral cancer cell line." (PMID 25091805, 2014). "To evaluate the expression level of DEPDC1B protein in oral cancer tissue, we performed an immunoblotting assay using human oral cancer tissue." (PMID 25091805, 2014). "Our results suggested a novel route by which DEPDC1B regulates Rac1 activation and modulates ERK1/2 activities, and offer an explanation for the mechanism by which DEPDC1b contributes to anchorage-independent growth in oral cancer cells." (PMID 25091805, 2014). "We used migration and invasion assays to confirm the role of DEPDC1B in oral cancer cell migration and invasion." (PMID 25091805, 2014). "We revealed a novel DEPDC1B-Rac1-ERK1/2 signaling axis in the development of oral cancer cell lines." (PMID 25091805, 2014). "We described a finding that revealed DEPDC1B proteins were overexpressed in oral cancer tissue, compared with normal adjacent tissue, in 6 out of 7 patients." (PMID 25091805, 2014). "DEPDC1B, acted as a potentially oncogenic protein in oral cancer patients, contributing to the sustained elevation of ERK1/2 activity throughout the stimulation of the GDP-GTP exchange in Rac1." (PMID 25091805, 2014). "The data suggested that when DEPDC1B was expressed in oral cancer cells, cellular motility and invasion ability was stimulated." (PMID 25091805, 2014). "The data suggested that DEPDC1B proteins stimulated anchorage-independent growth in an oral cancer cell line." (PMID 25091805, 2014). "We found that DEPDC1B was highly expressed in oral cancer tissue, compared with normal adjacent tissue." (PMID 25091805, 2014). "The results suggested that ERK activity mediates growth promotion induced by the expression of DEPDC1B and Rac in oral cancer cells." (PMID 25091805, 2014). "For all the MAPK pathways tested, we observed that the expression of DEPDC1B proteins in oral cancer cells induced p38 MAPK and ERK activity; however, it suppressed JNK activation." (PMID 25091805, 2014).
oral cancer (continued). "We examined oral cancer tissue; 6 out of 7 oral cancer tissue test samples overexpressed DEPDC1B proteins, compared with normal adjacent tissue." (PMID 25091805, 2014). "By using genetic approaches, we provided evidence that DEPDC1B regulates anchorage-independent growth mediated through Rac1 in oral cancer cells." (PMID 25091805, 2014). "DEPDC1B affects the loading and augmentation of ERK1/2 activity by Rac1 GTP, which subsequently causes colony formation in oral cancer cells." (PMID 25091805, 2014). "We found that oral cancer samples overexpressed DEPDC1B proteins, compared with normal adjacent tissue." (PMID 25091805, 2014). "The anchorage-independent growth ability in soft agar of the mutant Rac1 (Rac1 N17) coexpressed with DEPDC1B in these cells and oral cancer cells was examined and compared with DEPDC1B cells." (PMID 25091805, 2014). "This overexpression signifies the potential utility of DEPDC1B as a biomarker for oral cancer." (PMID 40096320, 2025). "In addition, the relationship between abnormal DEPDC1B expression and breast cancer, oral cancer, non-small cell lung cancer and other malignant tumors has been reported." (PMID 32684847, 2020). "However, the authors concluded that oral cancer samples overexpressed DEPDC1B proteins, compared with normal adjacent tissue, and so DEPDC1B plays a role in the development of oral cancer." (PMID 31019584, 2019). "The precise function of DEPDC1B is uncharacterized; however, in recent studies it has been shown to promote cell growth, invasion, and anchorage-independent growth of oral cancer cells, the function being mediated by the direct physical interaction of DEPDC1B with Rac1 protein." (PMID 27034663, 2016). "Suggest that DEPDC1B plays a role in the development of oral cancer." (PMID 25091805, 2014). "To determine whether DEPDC1B played a role in the induction of cell proliferation in oral cancer cells, we examined the growth rate when cells were both with and without the DEPDC1B expression, in growth conditions of adhesion and non-adhesion." (PMID 25091805, 2014). "DEPDC1B was a guanine nucleotide exchange factor and induced both cell migration in a cultured embryonic fibroblast cell line and cell invasion in cancer cell lines; moreover, it was observed to promote anchorage-independent growth in oral cancer cells." (PMID 25091805, 2014). "To confirm the expression of DEPDC1B in such oral cells, we employed a PAK PBD pull-down assay to test whether the DEPDC1B expressed in oral cancer cells induced GTP loading in Rac1 proteins." (PMID 25091805, 2014). "Because the small GTPase Rac1 acted as a bridge for DEPDC1B to induce cellular functions, we tested the role of DEPDC1B to see whether it potentiated tumor formation in an oral cancer cell line, KB." (PMID 25091805, 2014). "Also, the identification of the possible allosteric or regulatory sites enhances our knowledge and thereby will play a crucial role in designing an appropriate drug that will have the potential of targeting the protein DEPDC1B and therefore curing the disease, that is, oral cancer." (PMID 27034663, 2016). "The data suggested that DEPDC1B may play a role in the development of oral cancer." (PMID 25091805, 2014). "DEPDC1B is a DEP domain-containing protein located on human chromosome 5q12, and is overexpressed in a variety of cancers, including oral cancer, prostate cancer, breast cancer and bladder cancer." (PMID 34983303, 2022). "Alterations in the EGFR gene copy number, or alterations in miR-7, miR-21, mRNA-KIFGA, OPN, DEPDC1B, EZH2, deltaNp63, and DNMT3B were significant for early evaluation and correlation with oral cancer." (PMID 31019584, 2019). "We found that DEPDC1B was a growth-promoting protein that activated Rac and then triggered ERK activity to enhance anchorage-independent growth in oral cancer cells." (PMID 25091805, 2014).
oral cancer (continued). "In oral carcinoma, however, due to disruption of HPV E2, which is a viral tumor suppressor and is known to downregulate the expression of DEPDC1B, highly expressed DEPDC1B could interact with RAC1 and result in cell invasion/metastasis." (PMID 35095994, 2021). "Our model suggested that DEPDC1B was a positive modulator of Rac1 in oral cancer cell lines cultured in both adherent and nonadherent conditions." (PMID 25091805, 2014).